RGS16 (regulator of G protein signaling 16)
Diseases named in the same sentence as RGS16 in open-access papers (continued):
Sharing a sentence is not in itself a finding about the gene and the disease.
pancreatic cancer (continued). "This suggests that RGS16 may be used as a prognostic marker for pancreatic cancer and PDA." (PMID 36120550, 2022). "A previous report using tissue microarray analysis revealed decreased expression of Regulator of G-protein signaling 16 (RGS16) in pancreatic tumors with lymph-node metastases compared to nonmetastasized pancreatic cancer and this loss was associated with decreased patient survival." (PMID 25568667, 2014). "Currently, RGS16 has not been linked with inhibition of cancer cell metastasis nor has its function been investigated to understand it's downregulation in metastasized pancreatic cancer." (PMID 25568667, 2014). "In addition, the mRNA and protein levels of RGS16 were reported to be higher in colorectal cancer tissues than in the corresponding normal tissues; therefore, RGS16 may be considered a predictive marker for cancers such as colorectal and pancreatic cancers." (PMID 37924113, 2023). "Future studies are needed to determine if RGS16 can inhibit cell migration and invasion through other pathways such as the SDF-1/CxCR4 pathway which is deregulated in pancreatic cancer." (PMID 25568667, 2014). "RGS16 has been found to be downregulated in pancreatic cancer patients with metastases compared to patients without metastasis." (PMID 25568667, 2014).
colorectal cancer (6 papers, 2017 to 2023). A primary or metastatic malignant neoplasm that affects the colon or rectum. "Three of these genes (Rgs16, Rassf3 and Fam13a) are members of the RAC/RHO/RAS pathway, and dysregulated Rgs16 has been associated with poor prognosis in colorectal cancer." (PMID 28219480, 2017). "RGS16 has already been reported to possess a higher expression level in colorectal cancer tissue than in the corresponding normal tissue and serves as an unfavorable prognostic marker." (PMID 36925652, 2023). "The expression level of RGS16 mRNA and protein in colorectal cancer tissues were much higher than that in normal tissues." (PMID 32319728, 2020). "In colorectal cancer, RGS16 exerts completely different biological functions." (PMID 32319728, 2020).
atherosclerosis (4 papers, 2016 to 2024). A disease characterized by the build-up of fatty material and calcium deposition in the arterial wall resulting in partial or complete occlusion of the arterial lumen. "Lastly, miR-126a-3p has also a regulatory role for the expression of CXCL12 via the inhibition of CXCR4 by RGS16, a signaling pathway that is involved in atherosclerosis and inflammation." (PMID 26956024, 2016). "For example, miR-126-3p derived from EC apoptosis bodies suppresses the production of regulator of G-protein signaling 16 (RGS16) to activate CXCL12 and its receptor CXCR4, weakening atherosclerosis." (PMID 37418054, 2024). "For instance, miR-126-3p delivered by EC apoptosis bodies inhibits expression of regulator of G-protein signaling 16 (RGS16) to activate C-X-C motif chemokine ligand 12 (CXCL12) and its receptor, C-X-C motif chemokine receptor 4 (CXCR4), thereby reducing atherosclerosis." (PMID 33391525, 2021).
Hepatic steatosis (4 papers, 2019 to 2021). Steatosis is a term used to denote lipid accumulation within hepatocytes. "RGS16 has been shown to induce hepatic steatosis by inhibiting Gi/Gq-mediated fatty acid oxidation." (PMID 32075112, 2020). "We next examined the hypothesis that genetic reconstitution of hepatic RGS16 in the context of Arg2 overexpression would reverse the improvements in hepatic steatosis, inflammation and insulin and glucose intolerance observed in Arg2-treated db/db mice." (PMID 30962478, 2019). "Of significance, both Rgs16 and Lpin1 were identified by IPA® analysis as part of a subset of molecules affecting liver steatosis in the SHS-exposed mice." (PMID 32075112, 2020).
acute lymphoblastic leukemia (3 papers, 2014 to 2022). Leukemia with an acute onset, characterized by the presence of lymphoblasts in the bone marrow and the peripheral blood. "Finally, RGS16 protein is aberrantly expressed in hyper diploid acute lymphoblastic leukemia, suggesting that RGS16 may be involved in hematologic malignancies." (PMID 36120550, 2022). "Some of these genes have already been shown to play a role in hematologic malignancies, including CLL (Pim-2, Met, Rgs16, Ccdc88a, Zcchc18, Clip3), diffuse large B cell lymphoma, follicular lymphoma (Vav3), acute lymphoblastic leukemia (ALL) (Itm2a, Chst1) or acute myeloid leukemia (AML) (Chd3)." (PMID 30271400, 2018). "Although increased expression of RGS16 has been found in pediatric high hyperdiploid acute lymphoblastic leukemia (ALL) and colon cancer, functional analysis of RGS16 has not been performed to identify any oncogenic function in these cancers." (PMID 25568667, 2014).
breast tumors (2 papers, 2014 to 2022). "On the contrary, high RGS16 expression in breast tumors attenuates the growth factor-induced PI3K signaling pathway, thereby inhibiting proliferation, human epidermal growth factor receptor 2 activation and resistance to chemotherapeutic agents in breast tumor cells." (PMID 36120550, 2022).
gastric cancer (2 papers, 2025). A primary or metastatic malignant neoplasm involving the stomach. "Moreover, RGS16 was upregulated in gastric cancer, and overexpression of RGS16 showed the effect of reducing elevated ROS." (PMID 41011126, 2025).
Insulin resistance (2 papers, 2019 to 2021). Increased resistance towards insulin, that is, diminished effectiveness of insulin in reducing blood glucose levels. "Accordingly, Rgs16 reconstitution substantially exacerbated insulin resistance in db/db mice as defined by serum insulin, glucose, and HOMA2-IR." (PMID 30962478, 2019).
lung carcinoma (2 papers, 2005 to 2022). "Our data suggest that RA-induced changes in the expression of RARβ2, CYP26A1, CRBP1, RGS16, DUSP6, and EGR1 may be necessary for the retinoid anticancer signal in neuroblastoma, breast and/or lung cancer cells." (PMID 16012519, 2005). "However, RGS16, RARβ2, and CYP26A1 were not detectable and not RA inducible in both of the RA-resistant breast and lung cancer cells." (PMID 16012519, 2005).
melanoma (2 papers, 2018 to 2022). A malignant, usually aggressive tumor composed of atypical, neoplastic melanocytes. "RGS16 KO mice developed larger primary tumors than WT mice after injection of melanoma cells, indicating that RGS16 expressed in the tissues surrounding the tumor has a protective effect." (PMID 30526524, 2018). "B16F10-luc melanoma cells expressing stably luciferase were injected subcutaneously into WT and RGS16 KO mice, and tumor progression was monitored for 28 days." (PMID 30526524, 2018). "Although the expression of Regulator of G protein Signaling (RGS)-16 by recipient mice inhibited the development of grafted melanoma in vivo, it was not required for the antitumoral activity of ORF3." (PMID 30526524, 2018). "We also examined whether Regulator of G protein Signalling 16 (RGS16), which binds specifically to PCV2 ORF3 and may be involved in oncogenic pathways, modulates the effect of apoptin on melanoma growth." (PMID 30526524, 2018). "Since ORF3 of PCV2 interacts directly with the RGS16 and a number of studies have shown a role for RGS16 in the pathogenesis of several cancers, we tested whether RGS16 might be involved in the ORF3-mediated inhibition of melanoma growth." (PMID 30526524, 2018).
neuroblastoma (2 papers, 2005 to 2014). Neuroblastoma (NB) is the most common solid, extracranial childhood tumor. "RGS16 has also been associated in the anti-proliferative effect of retinoic acid in neuroblastoma cells and the cytotoxic effect of histone deacetylase inhibitor Vorinostat in triple negative breast cancers." (PMID 25568667, 2014). "Combined, rather than individual, inhibition of DUSP6 and RGS16 was required to block retinoid-induced growth inhibition in neuroblastoma cells, through phosphorylation of extracellular-signal-regulated kinase." (PMID 16012519, 2005).
ovarian carcinoma (2 papers, 2022 to 2024). A malignant neoplasm originating from the surface ovarian epithelium. "Additionally, a recent study has suggested that RGS16 can be used as a diagnostic biomarker for immune subtypes of ovarian cancer and as a biomarker to predict the clinical stage of the disease." (PMID 36120550, 2022).
schizophrenia (2 papers, 2022 to 2024). A major psychotic disorder characterized by abnormalities in the perception or expression of reality. "Therefore, this study aims to provide an in-depth analysis and visualization of RGS16-related research between 1995 and 2022 and to assess the current state and future trends of research in this field (mainly cancer, inflammation, and schizophrenia)." (PMID 38363937, 2024).
atopic dermatitis (1 paper, 2020). "Again, RGS16 dysregulation has been linked to chronic inflammatory skin pathologies including psoriasis and atopic dermatitis." (PMID 33489929, 2020).
contact dermatitis (1 paper, 2024). An inflammatory skin condition caused by direct contact between the skin and either an irritating substance or an allergen. "The role of RGS16 in allergic and irritant contact dermatitis is currently only used as a marker to distinguish between the 2 diseases." (PMID 38363937, 2024).
depression (1 paper, 2024). "Multiple identified genes, such as RNASEL, RGS16, RFX4 and ROBO2 were reported to be associated with chronotype, depression or cognition in previous studies." (PMID 38778419, 2024). "Thus, RFX4, RGS16, RNASEL and ROBO2 may be the important genetic factors indirectly linked to sleep disturbances and depression via circadian rhythm or neurotransmitters." (PMID 38778419, 2024). "We identified several candidate genes for sleep disorders in the subjects with depression, such as RFX4, RGS16 and ROBO2." (PMID 38778419, 2024). "GWAS detected 15 loci significantly associated with chronotype in the subjects with self-reported depression, such as rs12736689 at RNASEL (P = 1.00 × 10− 09), rs509476 at RGS16 (P = 1.58 × 10− 09) and rs1006751 at RFX4 (P = 1.54 × 10− 08)." (PMID 38778419, 2024). "Moreover, study supported the association between RGS16/RNASEL and neuroticism, although they are not directly related to depression." (PMID 38778419, 2024).
diabetes (1 paper, 2022). "RGS16 and RGS8 are expressed in embryonic pancreatic progenitor and endocrine cells and disappear in adults; however they are reactivated in type I and II diabetes models, which suggests that the RGS16 and RGS8 proteins may become a novel target for further treatment of diabetes." (PMID 36120550, 2022).
esophageal cancer (1 paper, 2025). A primary or metastatic malignant neoplasm involving the esophagus. "It has been documented that RGS16 modulated Hippo-YAP activity to fuel esophageal cancer cell proliferation and migration." (PMID 40413527, 2025).
esophageal squamous cell carcinoma (1 paper, 2025). Esophageal squamous cell carcinoma (ESCC) is a type of esophageal carcinoma (EC) that can affect any part of the esophagus, but is usually located in the upper or middle third. "Recent studies have identified that abnormally increased expression of RGS16 in esophageal squamous cell carcinoma RGS16 promotes cancer progression by affecting cell proliferation." (PMID 41011126, 2025).
glioblastoma (1 paper, 2020). The most malignant astrocytic tumor (WHO grade IV). "Functional analysis of RGS16 was performed in several glioblastoma (GBM) cell lines." (PMID 32319728, 2020).
hepatitis B (1 paper, 2022). "The association of the RGS16 protein with immune, inflammatory, tumor and metabolic disorders has been well established, and the RGS16 protein may also be involved in hepatitis B -induced inflammatory response." (PMID 36120550, 2022).
hepatocellular carcinoma (1 paper, 2024). A malignant tumor that arises from hepatocytes. "Based on the study of RGS16 in oncology, we found that there are still new research advances in PATHOLOGY and SURGERY, mainly including signature, PD 1, bone calcium, histone deacetylase inhibitor, gene signature, gemcitabine, hepatocellular carcinoma, and pancreatic ductal adenocarcinoma." (PMID 38363937, 2024).
insomnia (1 paper, 2020). A sleep disorder characterized by difficulty in falling asleep and/or remaining asleep. "For instance, RGS16 has been recently implicated in insomnia, and knockout of this gene in mice disrupts circadian regulation." (PMID 33007266, 2020).
irritant contact dermatitis (1 paper, 2024). "According to Fortino, it is considered that Random Forest Classification identified RGS16 and 21 different proteins as potential biomarkers to distinguish allergic and irritant contact dermatitis in human skin." (PMID 38363937, 2024).
osteosarcoma (1 paper, 2014). A usually aggressive malignant bone-forming mesenchymal neoplasm, predominantly affecting adolescents and young adults.
ulcerative colitis (1 paper, 2024). An inflammatory bowel disease involving the mucosal surface of the large intestine and rectum. "The biological applications of RGS16 are currently a hot area of RGS16 research, including inflammation, cancer, ulcerative colitis, metabolic acidosis, platelet activation, and thrombosis." (PMID 38363937, 2024).
tumor (21 papers, 2005 to 2025). "The IHC staining results revealed that the Ki67 level, a protein associated with tumor proliferation, was reduced following the knockdown of RGS16." (PMID 40413527, 2025). "By contrast, the seven TCGA tumor samples with highest Rgs16 expression all harbored oncogenic Kras alleles and were among the clades most related to mouse PDA cells by whole transcriptome analysis." (PMID 33244070, 2020). "Moreover, we found that elevated RGS16 expression was associated with tumor stage, T stage, N stage, and grade of differentiation, but not with distant metastasis." (PMID 38906869, 2024). "The findings from the UALCAN database indicated that RGS16 expression in 415 primary tumor samples was markedly higher, approximately 3-fold compared to that in 34 normal samples." (PMID 40413527, 2025). "Further animal experiments were carried out to elucidate the functional role of RGS16 in tumor growth." (PMID 40413527, 2025). "Strikingly, it was illustrated that the knockdown of RGS16 reinforced ferroptosis of GC cells, which implied that RGS16 played a role in promoting tumor progression by inhibiting ferroptosis." (PMID 40413527, 2025). "By recording the changes in tumor volume within 25 days, it was observed that the tumor volume expansion of mice subject to sh-RGS16 treatment was decelerated in contrast to that of mice having received sh-NC treatment." (PMID 40413527, 2025). "Together, these results demonstrated that the downregulation of RGS16 hindered the tumor growth of GC in vivo." (PMID 40413527, 2025). "Using the GEO database, the genes upregulated in GC were screened (GSE79973), and it was found that the RGS16 gene was upregulated in tumor tissues." (PMID 40413527, 2025). "In patients with CRC, RGS16 serves as a prognostic marker and predictor of tumor progression, potentially representing a future therapeutic target." (PMID 38906869, 2024). "On the other hand, recently, the effects of RGS16 on the anti-tumor activity of CD8+ cells were examined." (PMID 38203748, 2024). "Our investigation revealed that RGS16 overexpression significantly augmented tumor burden, whereas RGS16 knockdown markedly curtailed tumor growth in vivo." (PMID 38906869, 2024). "Expression of RGS16 has been reported to vary across multiple tumor types such as breast cancer, pancreatic cancer tissue, neuroblastoma, and others, either increasing or decreasing, suggesting its unique functional role." (PMID 38906869, 2024). "RGS16 plays an important role in tumor development and is expected to be a potential therapeutic target for regulating tumor process." (PMID 38363937, 2024). "The HRI signature consists of 11 HRDEGs, and we focused on the 5 key genes (RGS16, SNAI1, CDR2L, FRMD5, and FSTL3), which exhibited elevated expression levels in tumor tissues and are prognostic risk factors for CC." (PMID 36925652, 2023). "In the case of RGS2, the expression was the highest in tumor cells treated with 300 ng/mL of paclitaxel and, for the RGS16, the difference was the highest for 60 ng/mL." (PMID 35453754, 2022). "Despite its simple structure, the studies discussed in the present review suggest that RGS16 is an important regulator in immune, inflammatory, tumor, biological rhythm and metabolic disorders, and coagulation dysfunction." (PMID 36120550, 2022). "Rgs16 deficiency inhibits CD8+ T cell apoptosis and acts synergistically with PD-1 blockade in enhancing anti-tumor CD8+ T cell responses." (PMID 36269001, 2022). "Rgs16::GFP expression is KrasG12D-dependent in the earliest ductal neoplasia (P18) in KC and KIC mice." (PMID 33244070, 2020). "We found that the expression level of RGS16 was positively correlated with tumor grade and significantly upregulated in mesenchymal subtype, which is generally considered to have a poor prognosis." (PMID 32319728, 2020).